ENSG00000253072
Gene: Small nucleolar RNA gene on chromosome 11 (15,481,808 to 15,481,893, reverse strand). Ensembl gene ENSG00000253072.
Homologues: Paralogues in human: SNORD68 (66% identical).